WSCD2 (WSC domain sialate O sulfotransferase 2)
Description:
Sialate:O-sulfotransferase which catalyzes 8-O-sulfation at the Sia-glycan level using 3'-phosphoadenosine 5'-phosphosulfate (PAPS) as a donor, forming 8-O-sulfated Sia (Sia8S)-glycans. Displays selectivity toward glycoproteins such as TF/transferrin.
Synonyms: KIAA0789
Tractability: Antibody: UniProt predicts a signal peptide or a membrane-spanning region.
Gene: Protein-coding gene on chromosome 12 (108,129,288 to 108,250,537, forward strand). Ensembl gene ENSG00000075035.
Subcellular location: Golgi apparatus membrane
Subcellular location (Human Protein Atlas): Nucleoplasm
Gene Ontology:
Molecular function: sulfotransferase activity
Cellular component: Golgi membrane
Genetic constraint (gnomAD): Loss-of-function variants: 24 observed, 51.66 expected, observed/expected ratio (o/e) 0.46, 90% interval 0.34 to 0.65. The upper end of that interval is the gene's LOEUF score, 0.65, which puts it in group 2 of 6, group 1 being the genes least tolerant of losing a copy. Missense variants: 475 observed, 635.86 expected, observed/expected ratio (o/e) 0.75, 90% interval 0.69 to 0.81. Synonymous variants: 234 observed, 252.03 expected, observed/expected ratio (o/e) 0.93, 90% interval 0.83 to 1.03.
Homologues: Orthologues: chimpanzee WSCD2 (99% identical), macaque WSCD2 (99% identical), pig WSCD2 (97% identical), guinea pig WSCD2 (96% identical), rabbit WSCD2 (95% identical), mouse Wscd2 (93% identical), rat Wscd2 (92% identical), tropical clawed frog wscd2 (78% identical), zebrafish wscd2 (72% identical), Drosophila melanogaster CG9164 (20% identical), Drosophila melanogaster oxt (13% identical), Caenorhabditis elegans sqv-6 (11% identical), and 16 more. Paralogues in human: WSCD1 (48% identical), XYLT1 (19% identical), XYLT2 (18% identical), GCNT1 (9% identical), GCNT4 (8% identical), GCNT3 (8% identical), GCNT2 (7% identical), GCNT7 (6% identical).
Diseases named in the same sentence as WSCD2 in open-access papers:
WSCD2 is named in the same sentence as 12 diseases in open-access papers, as found by Europe PMC text mining. Sharing a sentence is not in itself a finding about the gene and the disease. The quoted sentences say what the papers report.
breast carcinoma (3 papers, 2022 to 2025). "Analysis of bulk RNA-Seq revealed a decrease in WSCD2 gene expression in the samples from TCGA breast cancer patients with the genotype homozygous for the minor alleles and core gene networks of transcription factors, growth factors and insulin indirectly associated with MT-ND4." (PMID 35082309, 2022). "However, WSCD2 has no known function and there is insufficient biological information to theorize a likely mechanism of how WSCD2 gene expression can play a role in the effect of nuclei size or how the mito-nuclear interaction contributes to the pathogenesis of breast cancer." (PMID 37639552, 2023).
cardiac arrhythmia (1 paper, 2022). Any disturbances of the normal rhythmic beating of the heart or MYOCARDIAL CONTRACTION. "In contrast, Wscd2(−/−) fry did not develop cardiac arrhythmia, or any changes in MHC levels compared to the WT and Wscd2(+/−) fry." (PMID 35864127, 2022).
glioblastoma (1 paper, 2022). The most malignant astrocytic tumor (WHO grade IV). "The four tumor-related genes (TNFAIP6, C15orf48, WSCD2, and CBLN1) were neither reported in ferroptosis-related reports nor in glioblastoma-related studies, which were first found by us." (PMID 35720126, 2022).
glioma (1 paper, 2025). A benign or malignant brain and spinal cord tumor that arises from glial cells (astrocytes, oligodendrocytes, ependymal cells). "Using TCGA and Genotype-Tissue Expression (GTEx) datasets, we found that the mRNA expression of the WSC domain-containing 2 (WSCD2) gene was not only related to the prognosis of patients with glioma but also linked to immune infiltration in glioma tissues." (PMID 38415455, 2025). "Based on TCGA database and GTEx data, GEPIA2 revealed that WSCD2 mRNA expression in glioma tissues was lower than that in benign brain tissues (log2FC < 1, p < 0.01)." (PMID 38415455, 2025). "In this study, we carried out bioinformatics analysis to examine the expressions of WSCD2 mRNA and TILs in glioma." (PMID 38415455, 2025). "We analyzed WSCD2 mRNA expression in glioma tissues and patient survival using the Gene Expression Profiling Interactive Analysis database." (PMID 38415455, 2025). "In the case of the differential WSCD2 expression in glioma tissues, it was observed that higher WSCD2 protein expression was strongly related to lower tumor grade and positive outcomes." (PMID 38415455, 2025). "This study aimed to investigate the relevance of WSC domain-containing 2 (WSCD2) expression to glioma, clinicopathological characteristics, tumor-infiltrating immune cells (TILs), and patient prognosis." (PMID 38415455, 2025). "Furthermore, the level of WSCD2 protein in glioma tissues was lower than that in tissues of benign brain disease, with a significant difference (t = 2.104, p = 0.003) via the Student's t-test." (PMID 38415455, 2025). "WSCD2 mRNA expression in glioma tissues was lower than that in tissues of benign brain disease." (PMID 38415455, 2025). "Additionally, WSCD2 mRNA expression was correlated with TIL expression in glioma; however, no such relationship was detected between the protein expressions of WSCD2 and TILs in glioma tissues." (PMID 38415455, 2025). "Furthermore, the relationship between the expressions of WSCD2 mRNA and TILs in gliomas was evaluated utilizing the Tumor Immune Estimation Resource database." (PMID 38415455, 2025).
knee osteoarthritis (1 paper, 2023). "Two high-confidence effector genes, WSCD2 and TMEM119, reside in the same genomic locus, which colocalizes for type 2 diabetes and knee osteoarthritis with a posterior probability of 99.9%." (PMID 37433298, 2023).
thyroid cancer (1 paper, 2016). "Other notable genes of unknown function within this list were WSCD2 and IQGAP2, which have previously been reported as downregulated in thyroid cancer." (PMID 27633254, 2016).
cancer (2 papers, 2022 to 2025). A tumor composed of atypical neoplastic, often pleomorphic cells that invade other tissues. "Additionally, WSCD2 is involved in glucose metabolism, which, in turn, is related to cancer aggressiveness." (PMID 38415455, 2025).
psychiatric disorder (1 paper, 2021). A disorder characterized by behavioral and/or psychological abnormalities, often accompanied by physical symptoms. "Interestingly, genome wide association analyses found significant results for variants in WSCD2 in patients with psychiatric disorders." (PMID 34621295, 2021).
WSCD2 also shares sentences with these, for which no sentence is quoted: tumor (3 papers); brain disease (1); depression (1); type 2 diabetes (1).